ITK (IL2 inducible T cell kinase)
Description:
Tyrosine kinase that plays an essential role in regulation of the adaptive immune response. Regulates the development, function and differentiation of conventional T-cells and nonconventional NKT-cells. When antigen presenting cells (APC) activate T-cell receptor (TCR), a series of phosphorylation lead to the recruitment of ITK to the cell membrane, in the vicinity of the stimulated TCR receptor, where it is phosphorylated by LCK. Phosphorylation leads to ITK autophosphorylation and full activation. Once activated, phosphorylates PLCG1, leading to the activation of this lipase and subsequent cleavage of its substrates. In turn, the endoplasmic reticulum releases calcium in the cytoplasm and the nuclear activator of activated T-cells (NFAT) translocates into the nucleus to perform its transcriptional duty. Phosphorylates 2 essential adapter proteins: the linker for activation of T-cells/LAT protein and LCP2. Then, a large number of signaling molecules such as VAV1 are recruited and ultimately lead to lymphokine production, T-cell proliferation and differentiation. Required for TCR-mediated calcium response in gamma-delta T-cells, may also be involved in the modulation of the transcriptomic signature in the Vgamma2-positive subset of immature gamma-delta T-cells (By similarity). Phosphorylates TBX21 at 'Tyr-530' and mediates its interaction with GATA3 (By similarity).
Synonyms: EMT; LYK; PSCTK2; LPFS1
Tractability: Small molecule: an approved drug acts on it; a structure with a bound ligand is known; a high-quality ligand is known; it has a high-quality binding pocket; it belongs to a druggable protein family. Antibody: its Gene Ontology location is reachable by antibodies, with medium confidence. PROTAC: it is named in the literature on targeted protein degradation; UniProt records ubiquitination sites on it; ubiquitination databases record sites on it; its protein half-life has been measured; a small molecule that binds it is known.
Target class: TK protein kinase group; Kinase; Protein Kinase; Enzyme; Tyrosine protein kinase Tec family
Chemical probes: BMS-509744 (high quality), GNE-9822 (high quality), PD081636
Gene: Protein-coding gene on chromosome 5 (157,142,933 to 157,255,185, forward strand). Ensembl gene ENSG00000113263.
Subcellular location: Cytoplasm; Nucleus
Subcellular location (Human Protein Atlas): Cytosol
Pathways (Reactome):
Immune System: FCERI mediated Ca+2 mobilization; Generation of second messenger molecules
Gene Ontology:
Molecular function: non-membrane spanning protein tyrosine kinase activity; protein binding; ATP binding; protein kinase activity; protein tyrosine kinase activity
Biological process: adaptive immune response; B cell receptor signaling pathway; cellular defense response; gamma-delta T cell activation; NK T cell differentiation; positive regulation of cytokine production; signal transduction; T cell activation; T cell receptor signaling pathway; intracellular signal transduction
Cellular component: cytosol; nucleus; plasma membrane; cytoplasm
Genetic constraint (gnomAD): Loss-of-function variants: 32 observed, 66.73 expected, observed/expected ratio (o/e) 0.48, 90% interval 0.36 to 0.64. The upper end of that interval is the gene's LOEUF score, 0.64, which puts it in group 2 of 6, group 1 being the genes least tolerant of losing a copy. Missense variants: 522 observed, 689.36 expected, observed/expected ratio (o/e) 0.76, 90% interval 0.7 to 0.81. Synonymous variants: 263 observed, 248.42 expected, observed/expected ratio (o/e) 1.06, 90% interval 0.96 to 1.17.
Gene-disease validity (ClinGen):
ClinGen rates the evidence that ITK causes each of these diseases.
lymphoproliferative syndrome 1 (autosomal recessive): Definitive. A condition of decreased or absent presence or activity of IL2-inducible t-cell kinase.
Homologues: Orthologues: chimpanzee ITK (99% identical), macaque ITK (99% identical), dog ITK (95% identical), guinea pig ITK (95% identical), rat Itk (95% identical), rabbit ITK (94% identical), mouse Itk (94% identical), pig ITK (92% identical), tropical clawed frog itk (67% identical), zebrafish itk (58% identical). Paralogues in human: TEC (58% identical), BTK (52% identical), BMX (48% identical), TXK (46% identical), ABL2 (29% identical), ABL1 (29% identical), BLK (29% identical), FGR (29% identical), HCK (28% identical), LCK (28% identical), FYN (28% identical), LYN (27% identical), and 20 more.
Diseases named in the same sentence as ITK in open-access papers:
ITK is named in the same sentence as 136 diseases in open-access papers, as found by Europe PMC text mining. Sharing a sentence is not in itself a finding about the gene and the disease. The quoted sentences say what the papers report.
hepatocellular carcinoma (23 papers, 2014 to 2025). A malignant tumor that arises from hepatocytes. "Previous studies have reported a strong association between ITK expression and poor prognosis in lung adenocarcinoma, breast cancer, hepatocellular carcinoma, and lymphoma." (PMID 37693315, 2023). "IL-2–inducible T cell kinase (ITK) protein, encoded by ITK, is a TEC (tyrosine kinase expressed in hepatocellular carcinoma) family tyrosine kinase expressed in T and NK lymphocytes and mast cells." (PMID 36326697, 2023). "Ibrutinib has the propensity to bind to other enzymatic structures similar to BTK that contain the target cysteine residue, such as IL-2-inducible T cell kinase (ITK), tyrosine kinase expressed in hepatocellular carcinoma (TEC), and hematopoietic cell kinase (HCK), resulting in off-target effects." (PMID 37745115, 2023). "Tec family includes five members: (I) tyrosine kinase expressed in hepatocellular carcinoma (TEC), (II) interleukin-2-inducible T cell kinase (ITK), (III) resting lymphocyte kinase (RLK), (IV) bone marrow expressed kinase (BMX), and (V) BTK." (PMID 38125430, 2023). "BTK is a member of the Tec family kinases, which contain interleukin-2-inducible T cell kinase (ITK), tyrosine kinase expressed in hepatocellular carcinoma (TEC), resting lymphocyte kinase (RLK), and bone marrow expressed kinase (BMX)." (PMID 33676527, 2021). "They include TEC (tyrosine kinase expressed in hepatocellular carcinoma), BTK (Bruton’s tyrosine kinase), ITK (IL2-inducible T-cell kinase), RLK (Resting lymphocyte kinase), and BMX (bone marrow-expressed kinase)." (PMID 34072040, 2021). "Four of them are TEC family kinase members: ITK, interleukin-2-inducible T-cell kinase; TEC, tyrosine kinase expressed in hepatocellular carcinoma; BMX, bone marrow-expressed kinase; and RLK/TXK, resting lymphocyte kinase/ T and X cell expressed kinase." (PMID 33777941, 2021). "Besides its intended BTK effects, ibrutinib also deactivates several off-targets, including epidermal growth factor receptor (EGFR), ErbB2, interleukin-2-inducible T cell kinase (ITK), and tyrosine kinase expressed in hepatocellular carcinoma (TEC)." (PMID 39518015, 2024). "While ibrutinib was primarily responsible for targeting BTK, it also inhibited several other kinases, including (Interleukin-2-Inducible T-Cell Kinase) ITK, (Tyrosine Kinase Expressed in Hepatocellular Carcinoma) TEC, and (Tyrosine Kinase Non-Receptor 1) TXK." (PMID 39062757, 2024).
lymphoma (20 papers, 2007 to 2026). A malignant (clonal) proliferation of B- lymphocytes or T- lymphocytes which involves the lymph nodes, bone marrow and/or extranodal sites. "These factors include immune dysregulation and an increased risk of developing lymphomas due to pathogenic variants of ITK and exposure to multiple chemo-radiotherapeutic treatments." (PMID 39684891, 2024). "Although in these cases the mutation of ITK led to the occurrence of lymphomas, there are also cases where an upregulation and activation of ITK occurs in already present tumours like in AITL or melanoma cells." (PMID 32808093, 2020). "To determine whether ACLY activity is required for PD-1-deficient lymphoma cell survival, we next incubated transformed ITK–SYK+PD-1− T cells from tamoxifen-injected ITK-SYKCD4-CreERT2;Pdcd1−/− mice with an ACLY inhibitor." (PMID 37723306, 2023). "Furthermore, enrichment of multiple gene expression signatures suggests enhanced glucose metabolism in the PD-1-deficient lymphoma cells compared to their premalignant ITK–SYK+PD-1+ counterparts." (PMID 37723306, 2023). "Therefore, similar to other related disorders associated with EBV infections (such as MAGT1 or ITK deficiency), the lymphoma incidence in STK4 deficient patients is assumed to be increased although the absolute number of reported cases, including the case presented here is still low (n = 3)." (PMID 30386345, 2018). "Given the identified pathogenic variants of ITK and the documented association between ITK disorders and EBV-related lymphomas, the Epstein–Barr encoding region (EBER) in situ hybridization was performed on a paraffin-embedded section of lymphoma in its onset." (PMID 39684891, 2024). "We detected a significant enrichment of c-FOS, FOSL1, FOSL2, c-JUN, and BATF target genes in H3K27ac ChIP–seq peaks upregulated in ITK–SYK+PD-1− lymphoma cells compared to their premalignant ITK–SYK+PD-1+ counterparts." (PMID 37723306, 2023). "In these studies, however, ITK inhibitor was evaluated either in activated T lymphoma cell lines or in primary murine T cells that were activated by anti-CD3 antibody." (PMID 37735204, 2023). "The in vivo antitumor activity of ITK inhibition was examined in SCID mice inoculated with H9 lymphoma cells." (PMID 30814910, 2019). "A preclinical study of ibrutinib, a small molecule inhibitor of mouse and human ITK, in established lymphoma was carried out and showed lymphoma regression in 8/12 (67%) mice." (PMID 31013298, 2019). "Based on our preclinical results, validation of drug combination synergy between ITK inhibitors and conventional chemotherapies employed in this study needs to be assessed in animal models of lymphoma." (PMID 30242208, 2018). "Based on the immunomodulatory effect in the clinical trial enrolled lymphoma patients, this study aims to explore the potential of the first in class highly selective ITK inhibitor soquelitinib in enhancing the persistence and antitumor functionality of CAR-T cells." (PMID 41792111, 2026). "ITK is essential for T-cell signaling and its defects result in an impaired T-cell responses, making individuals more vulnerable to infections and cancer, particularly lymphomas." (PMID 39684891, 2024). "The patient has an EBV-related lymphoma, confirmed by EBER in situ hybridization, which strengthens the hypothesis that the identified ITK deficiency predisposes the development of neoplasia, as reported in the literature." (PMID 39684891, 2024). "We asked whether AP-1 hyperactivity in ITK–SYK+PD-1− lymphoma cells is induced by ACLY activity and subsequently inflated acetyl-CoA pools." (PMID 37723306, 2023). "Moreover, treatment of ITK–SYK+PD-1− lymphoma-bearing mice with the mTOR inhibitor torin-1, which blocks mTOR activity within tumor cells in vivo, significantly prolonged survival (P = 0.0057)." (PMID 37723306, 2023). "This treatment killed ITK–SYK+PD-1− lymphoma cells (P = 0.0037)." (PMID 37723306, 2023).
lymphoma (continued). "T-cell receptor pathway may be correlated with the pathogenesis of extranodal NK/T-cell lymphoma, and the inducible T cell kinase (ITK) involved in T-cell receptor pathway may serve as a candidate target for treating the lymphoma patients expressing ITK." (PMID 36386851, 2022). "Furthermore, our observation that selected GATA-3 target genes, including c-Myc, CCR4, IKZF3 and ITK, are therapeutically targetable is noteworthy, as improved therapeutic strategies for these lymphomas are clearly needed." (PMID 36329027, 2022). "Despite the questionable effect of ITK inhibitors on lymphomas having been developed after viral infections, ITK is an important regulator of T cell development and activity and its inhibition could have beneficial effects on a variety of diseases, especially on autoimmune diseases." (PMID 32808093, 2020). "In humans, biallelic mutations in the ITK gene locus result in a monogenetic disorder leading to T cell dysfunction; in consequence, mainly EBV infections can lead to severe immune dysregulation evident by lymphoproliferation, lymphoma and hemophagocytic lymphohistiocytosis." (PMID 32808093, 2020). "ITK-SYK translocation triggers antigen-independent phosphorylation of TCR-proximal proteins, which has been confirmed to act as a powerful oncogenic driver in transgenic lymphoma mouse models." (PMID 30814910, 2019).
asthma (14 papers, 2013 to 2025). "The loss of ITK or its activity, either by mutation or through the use of inhibitors, has led to beneficial outcomes in experimental models of asthma, inflammatory bowel disease, and multiple sclerosis, among other diseases." (PMID 35980936, 2022). "The loss of ITK or its activity either by mutation or by the use of inhibitors led to a beneficial outcome in experimental models of asthma, inflammatory bowel disease and multiple sclerosis among others." (PMID 32808093, 2020). "Polymorphisms in the ITK promoter that increase ITK expression in humans have also been linked to increased asthma incidence." (PMID 26936133, 2016). "In addition, multiple murine models have demonstrated the importance of ITK in asthma and atopic dermatitis, e.g., the risk of atopic dermatitis was increased with the evaluated level of ITK." (PMID 38201909, 2023). "Inhibition of ITK by inhibitors has a certain beneficial effect on asthma, inflammatory bowel disease, and rheumatoid arthritis." (PMID 35190763, 2022). "Taken together, these findings suggest a potential role for ITK in active TB in humans, in addition to its known connection with primary immunodeficiency, susceptibility to EBV, lymphoproliferative diseases, and asthma." (PMID 32038633, 2019). "The available evidence suggests ITK is an attractive target for allergic diseases such as asthma and this has prompted us and numerous other pharmaceutical companies to generate inhibitors of this kinase." (PMID 25250764, 2014). "Future studies in our laboratory aim to test these separate models in order to further refine the requirement of ITK in asthma pathogenesis." (PMID 23667652, 2013). "In humans, only epidemiological studies have focused on SNPs in the ITK gene and the susceptibility to developing asthma without any further functional validation." (PMID 25339095, 2014). "In addition to a potential role in asthma, ITK may play a role in other allergic diseases and the pathogenesis of inflammatory skin diseases." (PMID 25250764, 2014). "The T cell number as well as the Th2 cytokines increased in the airways and therefore they suggested that the blocking of ITK in human patients with asthma would possibly not have any therapeutic effect." (PMID 32808093, 2020). "For example, the following were included: the inhibition of glucocorticoids on degranulation of mast cells in allergic asthma, inhibition of the kinase ITK in a mouse model of asthma reduces cell death, and the inhibition of CD38 gene-modified dendritic cells on murine asthma development." (PMID 30210753, 2018).
Sepsis (14 papers, 2020 to 2025). Sepsis is defined as life-threatening organ dysfunction caused by a dysregulated host response to infection. "Our data reveal increased p-ITK protein levels in circulating CD4+ T cells and ITK protein levels in the cerebral cortex, which are associated with sepsis-mediated neuroinflammation and depression-like symptoms." (PMID 37175808, 2023). "Our study shows that ITK plays an important role in sepsis-associated neuroinflammation through the modification of Th17-related signaling in the periphery and CNS." (PMID 37175808, 2023). "Our data show that sepsis causes increased ITK protein expression, IL-17A signaling, and neuroinflammatory mediators in the CNS that are associated with a depression-like state in mice." (PMID 37175808, 2023). "ITK inhibitor-treated mice with sepsis show attenuated IL-17A signaling, which is associated with the upregulation of IL-10/Nrf2 signaling and the amelioration of depression-like symptoms in mice." (PMID 37175808, 2023). "Sepsis is known to be associated with systemic inflammation and neuroinflammation in which ITK signaling may be involved; therefore, the modulation of ITK signaling in these phenomena was examined in this study." (PMID 37175808, 2023). "Further, the ITK inhibition approach was utilized to affirm whether ITK signaling was associated with depression-like effects in sepsis survivor mice." (PMID 37175808, 2023). "Oxidative inflammation is a major contributor in neuroinflammatory pathways associated with sepsis; therefore, we next explored whether ITK inhibition would lead to a modulation of the oxidative neuroinflammation." (PMID 37175808, 2023). "However, the role of ITK in sepsis-associated neuroinflammation and depression-like symptoms in mice has not been investigated earlier." (PMID 37175808, 2023). "Further, it was evaluated whether the ITK inhibitor also caused the downregulation of neuroinflammatory mediators in sepsis survivor mice." (PMID 37175808, 2023). "Our study shows a reduction in IL-17A levels with a concurrent abatement of neuroinflammation by the ITK inhibitor, which may be responsible for the amelioration in sepsis-associated depression-like behavior." (PMID 37175808, 2023). "Therefore, this study attempted to explore the role of ITK signaling in causing systemic inflammation and neuroinflammation associated with sepsis." (PMID 37175808, 2023). "However, sepsis-associated neuroinflammation remains uninvestigated with respect to ITK signaling." (PMID 37175808, 2023). "In a mouse model of induced sepsis, activation of the IL-2 inducible T-cell Kinase (ITK) signaling pathway elevated creatinine levels." (PMID 40286593, 2025). "ITK is involved in regulating thermal homeostasis in mast cell responses in LPS-induced sepsis, and its lack leads to hypothermia exacerbation." (PMID 38166628, 2024). "In the GSE65682 dataset, CD3E (AUC:0.9509), HLA-DRA (AUC:0.974), IL2RB (AUC:0.9931), ITK (AUC:0.9727) and LAT (AUC:0.9575) showed good diagnostic efficiency in distinguishing sepsis patients from healthy controls." (PMID 38166628, 2024). "Treatment with the ITK inhibitor caused a downregulation in the p-ITK+ CD4+ T cells and ITK levels in the CNS of sepsis survivor mice." (PMID 37175808, 2023). "Further, IL-10 and Foxp3 mRNA levels were also elevated in the cerebral cortex of sepsis survivor mice by the ITK inhibitor." (PMID 37175808, 2023). "Sepsis-induced elevation in the Th17-related parameters were attenuated by the ITK inhibitor in the periphery." (PMID 37175808, 2023). "The ITK inhibitor, BMS 509744, causes significant attenuation in sepsis-associated neuroinflammation and depression-like behavior through the downregulation of Th17-related mediators and oxidative stress in peripheral immune cells and the CNS." (PMID 37175808, 2023). "The sepsis-associated elevation in neuroinflammatory mediators, such as IL-6 and MCP-1, were greatly reduced in the CNS by the ITK inhibitor." (PMID 37175808, 2023).